INS (insulin)
Diseases named in the same sentence as INS in open-access papers (continued):
Sharing a sentence is not in itself a finding about the gene and the disease.
Insulin resistance (continued). "Diet-induced obese mice have an increased expression of inducible nitric oxide synthase (iNOS) and RNS generation in skeletal muscle such effects being associated with impaired insulin sensitivity, since mice with iNOS disruption in muscle are protected from insulin resistance induced by obesity." (PMID 22360800, 2012). "Two proteins involved in the insulin pathway (Annexin A2 and 14-3-3 ζ/δ) were found to be differentially expressed in the present study, and therefore may be directly associated with insulin resistance in GDM." (PMID 22970290, 2012). "Indeed, initial studies evaluated SST role on insulin hypersecretion as well as in hyperinsulinemia associated with obesity, two conditions that were described to induce insulin resistance." (PMID 23162532, 2012). "In either case, it is possible that improved glycemia may reduce glucose toxicity-associated insulin resistance and thereby increase insulin sensitivity." (PMID 22761701, 2012). "The HOMA-IR (homeostasis model assessment of insulin resistance) index was higher in rs1501299GG carriers as compared with TG and TT subjects, indicating higher insulin sensitivity in carriers of allele T, the same allele that showed an association with increased adiponectin levels." (PMID 22639977, 2012). "To determine whether impaired muscle insulin signaling caused by SOCS3 over-expression can be translated into systemic insulin resistance, we characterized the whole body insulin sensitivity of MCKSOCS3 mice fed a chow diet." (PMID 23115649, 2012). "Obesity is closely linked with insulin resistance, and increasing evidence suggests that reactive oxygen species (ROS) generated in muscle mitochondria may impair insulin signalling in animal and cellular models." (PMID 22586466, 2012). "The fact that fatty acid oxidation is impaired in insulin-resistant states led to the speculation that mitochondrial dysfunction is the cause of IMCLs accumulation and the ensuing insulin resistance." (PMID 22675355, 2012). "In addition, AOC3 activity is thought to ameliorate insulin resistance and is implicated in insulin signaling." (PMID 22238597, 2012). "Acidosis associated insulin resistance through cortisol activity may result in compensatory pancreatic insulin secretion and higher levels of circulating insulin in the serum, a condition known as hyperinsulinemia." (PMID 22853725, 2012). "Moreover, mice with a genetic disruption of endothelial NOS exhibit insulin resistance caused by reduction in both microvascular recruitment and muscle glucose uptake in response to insulin." (PMID 22558392, 2012). "Studies in animal models and in humans have demonstrated that obesity-associated insulin resistance as well as increased insulin requirements during pregnancy is matched by a corresponding stimulation in insulin output through β-cell hyperplasia and hypertrophy." (PMID 22919462, 2012). "The absence of association with HOMA-IR may be explained by the observation that the strongest association is found with type 2 diabetes, were both insulin resistance and impaired insulin secretion are present and necessary." (PMID 23227256, 2012). "Interestingly, T2DM increases risk to develop AD which is associated with reduced neuronal insulin sensitivity (central insulin resistance)." (PMID 23300647, 2012). "Additionally, in multivariate regression analysis, fasting glucose was associated only with insulin concentration and insulin resistance assessed by HOMA-index." (PMID 22577379, 2012). "It is also possible that oxidative stress may directly cause insulin resistance by damaging cellular components required for proper insulin signaling." (PMID 24764512, 2012). "But either insulin sensitivity or insulin resistance, associated with inactive TOR, is good." (PMID 22683661, 2012). "Since adipokines play an important role in insulin resistance, future studies on the interactions between adipokines and the insulin pathway may better elucidate underlying mechanisms." (PMID 22907422, 2012).
Insulin resistance (continued). "Regarding the association between insulin resistance and hyperandrogenism, studies with insulin sensitizers such as thiazolidinediones or metformin showed that significant reductions were observed in the secretion of A4 and 17-OHP in response to ACTH stimulation." (PMID 23216997, 2012). "Fasting hyperglycemia is associated with reduced hepatic insulin resistance and decreased first-phase insulin secretion, while elevated post-challenge glucose concentration is associated with peripheral insulin resistance and impairment of both early- and late-phase insulin response." (PMID 22731255, 2012). "We investigated whether common single nucleotide polymorphisms (SNPs) in the MAP4K4 locus associate with glucose intolerance, insulin resistance, impaired insulin release, or elevated plasma cytokines." (PMID 23094072, 2012). "In the liver, damage due to oxidative stress may cause insulin resistance by interfering with the ability of insulin to suppress hepatic glucose production." (PMID 22752055, 2012). "Interestingly, osteocalcin deficiency in knockout mice leads to decreased insulin and adiponectin secretion, insulin resistance, higher serum glucose levels, and increased adiposity." (PMID 23251132, 2012). "In the case of gestational diabetes, offspring have been shown to display reduced insulin secretion, while in the case of pre-existing diabetes, offspring have been shown to exhibit heightened insulin resistance, this possibly indicating a small difference in the underlying mechanisms." (PMID 23227034, 2012). "Moreover, obese subjects have increased levels of plasma FFA that are known to cause insulin resistance in all major insulin target organs." (PMID 21687689, 2011). "Patients with insulin resistance have loss of insulin signal transduction." (PMID 22389813, 2011). "Besides the established role of abnormal insulinsignaling in predisposing to insulin resistance, studies in animal modelshave proposed that insulin signaling is essential also for beta-cell insulinsecretion." (PMID 21573217, 2011). "An impairment of the initial steps in insulin signalling transduction pathways could contribute to the deficiency in insulin-stimulated glucose uptake in skeletal muscle, thus resulting in insulin resistance." (PMID 21489269, 2011). "Thus, it appears that diet and obesity place demands on β-cells for insulin by causing insulin resistance, but the genetic bottleneck that can lead to T2D involves genes that affect the capacity of pancreatic β-cells to meet the increased insulin demand." (PMID 21998599, 2011). "Weight loss improves insulin resistance by increasing insulin sensitivity." (PMID 21554710, 2011). "In turn, this could enhance mitochondrial biogenesis and fatty acid oxidation and upregulate insulin-associated signal transduction with subsequent improvement in insulin resistance." (PMID 20981161, 2011). "Interestingly, SNP rs7598660 was found to be weakly associated with several insulin and glucose related traits, such as 2 hour insulin levels, with the ancestral allele linked to higher insulin levels or greater insulin resistance." (PMID 22043170, 2011). "The mechanism underlying these discrepant effects of insulin on the platelets of healthy individuals versus patients with insulin resistance appears to be impairment of the insulin receptor signaling pathway that occurs not only in tissues but also in platelets." (PMID 21869886, 2011). "Overall, the observation that insulin resistance was attenuated by Ras inhibition in association with regulation of IκB and NF-κB provides a possible link between Ras, inflammation, and negative regulation of insulin signaling." (PMID 21738773, 2011). "Furthermore, we investigated the pathological consequences of the IR mutation related to systemic insulin resistance, because insulin signaling is generally regulated to the glucose metabolism in mammals." (PMID 21876806, 2011).
Insulin resistance (continued). "In addition, extrapolating these observations to the in vivo situation is complex and represents a balance of ‘direct’ GC actions to decrease lipogenesis as well as any potential action to cause insulin resistance and abrogate the effect of insulin treatment." (PMID 22022575, 2011). "To determine whether mitochondrial dysfunction induced by genetic or metabolic inhibition causes insulin resistance in hepatocytes, we analyzed the expression and insulin-stimulated phosphorylation of insulin signaling intermediates in SK-Hep1 hepatocytes." (PMID 21464990, 2011). "In addition to the cytokine-associated insulin resistance, the most abundant dietary saturated fatty acid palmitate can directly impair insulin signalling in muscle cells, reducing their insulin-dependent gain in surface GLUT4 and glucose uptake." (PMID 22046423, 2011). "In addition, a novel insulin resistance (IRAR) index was proposed by integration of the AR index into an existing insulin resistance index to provide an improved diagnostic biomarker of insulin sensitivity." (PMID 21251282, 2011). "Accordingly, our results suggest that low serum amylase levels may reflect metabolic abnormalities and abnormal glucose metabolism, both of which are associated with impaired insulin action due to insulin resistance and/or inadequate insulin secretion." (PMID 21496338, 2011). "In the current study, we examined the joint association of single nucleotide polymorphisms (SNPs) and copy number variants (CNVs) with fasting insulin and an index of insulin resistance (HOMA-IR) in the HyperGEN study, a family based study with proband ascertainment for hypertension." (PMID 21901158, 2011). "Type 2 diabetes is caused by a combination of impaired insulin secretion and insulin resistance, but their relative contribution to the development of hyperglycemia may differ due to the heterogeneity of this disease." (PMID 21569294, 2011). "It has been extensively studied that abnormally high levels of H2S may be linked to T2DM and insulin-resistance, which could mainly be accredited to its ability to inhibit both insulin secretion from pancreatic β-cells and glucose-uptake into adipocytes." (PMID 22216325, 2011). "An extension of these studies demonstrated that Mc4r-/- mice fed a high-fat diet developed severe hepatic steatosis and insulin resistance, characterized in part by impaired fasting glucose and insulin tolerance, suggesting that these mice were also susceptible to features associated with T2DM." (PMID 22043166, 2011). "For instance, obese humans and rodents develop ER stress in liver and adipose tissues, leading to insulin resistance whereas weight-loss decreases ER stress and improves insulin sensitivity, suggesting a correlation between ER stress and the metabolic syndrome." (PMID 22121381, 2011). "While Gln plays an important role in gluconeogenesis, evidence also suggests that Gln can improve insulin sensitivity and glucose disposal in patients suffering from critical illness, a condition frequently associated with insulin resistance and subsequent hyperglycemia." (PMID 22175008, 2011). "Therefore prevention of metabolic disorder caused by insulin resistance and improvement of insulin sensitivity are very important for the therapy of type 2 diabetes." (PMID 21935427, 2011). "The pathogenesis of insulin resistance involves a combination of genetic polymorphisms that influence insulin secretion and many acquired factors, such as sedentary lifestyle, medications, chronic illnesses, ageing, and other environmental factors which promote obesity and immobility." (PMID 21918648, 2011). "Associations between rs900400 and fasting serum insulin, fasting plasma glucose, insulinogenic index, homeostasis model assessment of insulin resistance (HOMA-IR) and disposition index were studied in 5,484 Danish and 6,915 Finnish non-diabetic individuals and combined in meta-analyses." (PMID 22073261, 2011).
Insulin resistance (continued). "While type 2 diabetes is linked with obesity, which increases insulin resistance and accelerates diabetes progression, insulin resistance leads to an enhanced sensitivity to the mitogenic effects of insulin, leading to a poorer prognosis in breast cancer patients." (PMID 22203527, 2011). "When only the data from those individuals with BMI values ≤25 were analyzed, the results were identical; insulin resistance was associated with increased JNK activation reduced insulin signaling, and elevated intramyocellular lipids, abdominal and visceral fat." (PMID 21589939, 2011). "Fasting insulin could be a sign of hyperinsulinaemia or insulin resistance and may contribute to cardiometabolic risk." (PMID 22050728, 2011). "Insulin resistance develops as a consequence of visceral adiposity and there is a rise in insulin production, which may be associated with activation of the insulin-like growth factor (IGF) system." (PMID 21696633, 2011). "Furthermore, the fact that LMNA mutations can cause both, severe insulin resistance and increased insulin sensitivity in target tissues, convincingly illustrates the pivotal role of A-type lamins in the regulation of glucose metabolism." (PMID 21738662, 2011). "However in GrOW, one haplotype, Hap6, was associated with effects on insulin levels and estimates of insulin resistance and sensitivity." (PMID 20227263, 2011). "Further investigations into the dual effects of ROS on insulin signaling may lead to the development of novel antioxidative therapies to selectively combat the oxidative stresses that cause insulin resistance." (PMID 22102892, 2011). "The vigorous ongoing debate regarding the association among chronic inflammation condition, insulin resistance and obesity provided a conflicting hypothesis that chronic inflammatory state originates from obesity and drives the insulin resistant condition." (PMID 21167068, 2010). "In the same persons we considered the influence of age on insulin, proinsulin, and the proinsulin/insulin ratio, after adjustment for the concomitant glucose concentrations, several covariates associated with insulin resistance, and the time since the last meal." (PMID 21162746, 2010). "Advanced renal damage may also in itself affect glucose metabolism and both cause insulin resistance and impair insulin secretion." (PMID 21162746, 2010). "The best known of these is that the MetS is a disorder of insulin sensitivity i.e. basically 'insulin resistance' and its sequelae, however it may be caused, as suggested by the IDF." (PMID 20513248, 2010). "IMCL content in the soleus muscle was found to be increased in insulin-resistant elderly patients, providing support for the hypothesis that an age-associated decline in mitochondrial function contributes to insulin resistance." (PMID 20596596, 2010). "Although the presence of an autoantibody does not necessarily mean an autoimmune disease, the functional characteristics of anti-PDI combined with the epidemiological associations with altered insulin metabolism suggest an autoimmune contribution to the pathogenesis of insulin resistance." (PMID 20886095, 2010). "Insulin resistance is paradoxically associated with a reduced ability of insulin signaling to inhibit glucose production, whereas insulin-stimulated lipogenesis is enhanced in the liver and two transcription factors, FoxO1 and FoxA2 play an important role in this process." (PMID 21994721, 2010). "The ability of SRA to regulate expression of genes related to inflammatory processes may be important in its effects on insulin sensitivity, since inflammation causes insulin resistance." (PMID 21152033, 2010). "Thus, a habitual consumption of excessive sugar intake causes a vicious cycle of hyperinsulinemia, insulin resistance, and increased compensatory insulin secretion, which can lead to beta-cell dysfunction and eventually type 2 diabetes." (PMID 20387989, 2010).
Insulin resistance (continued). "Additionally, ROS seems to be associated with insulin resistance in adipocytes, as normalisation of ROS levels reverses the inflammatory response and increases insulin sensitivity of these cells." (PMID 20948968, 2010). "Taken together, these differences might possibly contribute to a higher risk of developing hyperglycemia and hepatic insulin resistance in males as compared to females during situations of increased hepatic fat and/or insufficient insulin production." (PMID 20863371, 2010). "Both SOCS and JNK are negative regulators of insulin signaling and can cause insulin resistance." (PMID 21152033, 2010). "Insulin resistance may explain part of the possible association, because insulin and/or insulin resistance are hypothesized to be associated with hypertension by contributing to the pathogenesis of the disorder." (PMID 24281091, 2010). "Other causes could be selective mortality in elderly persons with elevated insulin due to impaired insulin action, or lower attendance rates in the older age groups because of illnesses associated with insulin resistance." (PMID 21162746, 2010). "This is further supported by the observation that mice with bone marrow-restricted disruption of cbl-associated protein (CAP), a downstream component of insulin action in control of glucose transport, are protected from obesity-associated inflammation and insulin resistance." (PMID 20463885, 2010). "Additionally, it has been reported that bone marrow-specific deletion of cbl-associated protein (CAP), a downstream molecule of the insulin signaling cascade, protects mice against obesity-induced insulin resistance." (PMID 20463885, 2010). "This may be associated with the development of insulin resistance, as children and adults who had low birth weight but are currently heavy are insulin resistant." (PMID 21197083, 2010). "As such, our current and previous data have highlighted an association between insulin and endotoxin, suggesting a mechanism that hyperinsulinemia/insulin resistance may lead to increased absorption of endotoxin through the GIT." (PMID 19368716, 2009). "MAPK has been implicated in T2D and plays a critical role in insulin signalling, and may contribute to insulin resistance." (PMID 19689793, 2009). "Insulin resistance is a metabolic disorder caused by decreased biological responses to insulin." (PMID 19646276, 2009). "Good SRH was associated with lower levels of inflammatory markers, insulin levels and insulin resistance, which might present SRH as a potential assessment tool to evaluate early deviations from health." (PMID 19788754, 2009). "Insulin and insulin resistance have been positively linked with AOM-induced carcinogenesis in rats." (PMID 19758446, 2009). "Conversely, low birth weight followed by rapid catch up growth was associated with down-regulation of insulin signalling proteins which may predispose these animals to insulin resistance later in life." (PMID 19308256, 2009). "Nonetheless, our findings are consistent with the notion that insulin resistance associated alterations in p70S6k regulation may be due, at least in part, to defects in the ability of insulin resistant muscle to activate mTOR following a contractile stimulus." (PMID 20368999, 2009). "In our study, insulin resistance measured by fasting insulin was similarly associated with MetS in both genders, showing a 22-fold risk in men and an 18-fold risk in women in the highest tertile of fasting insulin compared to the lowest tertile." (PMID 19707530, 2009). "More specifically, intramyocellular sphingolipids may cause insulin resistance by disrupting insulin signaling pathways in the muscle." (PMID 19936240, 2009). "Disturbances in the production of these factors may contribute to the development of insulin resistance or impaired insulin secretion: PPARγ activation is also associated with beneficial effects on the expression and secretion of a whole range of adipokines." (PMID 20182551, 2009).